SF3B1 (splicing factor 3b subunit 1)
Diseases named in the same sentence as SF3B1 in open-access papers (continued):
Sharing a sentence is not in itself a finding about the gene and the disease.
tumor (continued). "Similar to data observed in the Gq mutant UM cells, ectopic expression of mutant SF3B1, but not the wild‐type SF3B1, combined with BAP1 deletion strongly impaired tumor growth in a nude mouse xenograft model." (PMID 34706158, 2022). "A robust correlation between SF3B1 expression and the most critical oncogenic spliceosome components [SRSF3/RBM22/PTPB1/RBM3] was also found in GBM (CGGA- and Rembrandt-datasets), but not in the non-tumor samples (with the exception of PTBP1; Rembrandt-datasets)." (PMID 35086552, 2022). "This latter analysis revealed that Bcl-xS/Bcl-xL ratio was elevated after SF3B1 inhibition with pladienolide B in GBM in vivo (i.e., preclinical-xenograft GBM model) and GBM cells in vitro (U-87/U-118 MG cells and primary-GBM cell cultures), but not in an available primary non-tumor cell cultures." (PMID 35086552, 2022).
hematologic malignancies (36 papers, 2013 to 2026). "The results achieved based on the analyzed articles and reported in this article illustrated that SF3B1 is associated with hematologic malignancies, such as MDS, AML, and CLL more than BC." (PMID 36792691, 2023). "As a result of the conducted investigation, we realized that SF3B1 is association with hematologic malignancies, represented by (MDS, AML, and CLL) vs. BC." (PMID 36792691, 2023). "In this review, we took a snapshot of the current knowledge on the implications of SF3B1 mutations in different hematological malignancies." (PMID 36230848, 2022). "Among the spliceosome mutations, those in the SF3B1 gene are the most frequent and relevant in hematological diseases." (PMID 36230848, 2022). "Aiming to explore novel and selective inhibition strategies for SF3B1 mutations recurrent in hematologic malignancies we employed a cavity detector algorithm to pinpoint druggable (allosteric) sites, distinct from the BPA binding cavity." (PMID 34681880, 2021). "Overall, mutated SF3B1 has been detected in hematological malignancies and solid tumors and has been proven to be related to patient prognosis, abnormal transcription, alternative splicing, and sensitivity to SF3B small-molecule inhibitors." (PMID 32905346, 2020). "SF3B1 encodes a splicing factor frequently mutated in hematological malignancies, and with less frequency in other solid tumors." (PMID 31634348, 2019). "Considering the importance of Tregs in controlling immune responses, we determined how hematological malignancy-associated Sf3b1 mutation, Sf3b1-K700E in this case, affects the Tregs by using mice that express Sf3b1-K700E specifically in Tregs (Sf3b1K700Efl/+/Foxp3YFP-Cre)." (PMID 39303038, 2024). "However, mutations in the SF3B1 gene are the most common and significant among spliceosome mutations in hematological diseases." (PMID 40729294, 2024). "Investigating the reasons behind the difference may be useful for further understanding the role of SF3B1 mutations in hematological malignancies." (PMID 37511096, 2023). "Mutations in SF3B1 have been implicated as common drivers of hematologic malignancies." (PMID 32905346, 2020). "Notably, mutation of the other member of the U2AF complex (U2AF1) has been reported in the same hematologic malignancies associated with SF3B1 mutations." (PMID 30867899, 2019). "In order to understand the molecular and phenotypic consequences of SF3B1 mutations on hematopoiesis and their role in the pathogenesis of clonal blood disorders, we generated a knock-in conditional mouse model of SF3B1-K700E, the most common mutation in human MDS." (PMID 27604819, 2017). "Among these, H3B-8800, an oral small-molecule drug targeting SF3B1, has entered phase I clinical trials for the treatment of hematological malignancies." (PMID 40781225, 2025). "Of other hematologic malignancy-associated variants, ASXL1 was mutated in 5 of 144 (3.5%) and SF3B1 in 2 of 144 (1.4%) patients." (PMID 40179146, 2025). "Mutations in splicing factors, such as U2AF1, SF3B1, SRSF2, ZRSR2, and HNRNPH1, are frequently observed across various hematological malignancies and are associated with poor prognosis and treatment resistance." (PMID 39584923, 2024). "In this context, research efforts have been devoted to understanding the mechanism by which mutations of the splicing factor SF3B1 affect BPS recognition, thus leading to aberrant splicing and to the outbreak of distinct hematological malignancies." (PMID 31448284, 2019). "The SF3B1 and SF3A1 mRNA splicing factors have also been implicated in the pathogenesis of numerous hematologic malignancies." (PMID 24204290, 2013). "Notably, mutations in spliceosomal genes such as SF3B1, U2AF1, SRSF2, ZRSR2, and the RNA-stabilizing methyltransferase METTL3 are specifically enriched in haematological disease." (PMID 40495353, 2025).
hematologic malignancies (continued). "Relationship between AKT3 and mutations related to MDS or MPN hematological disorders The MDS- or MPN-related mutations affect genes involved in different molecular aspects of gene expression including RNA splicing (SRSF2, U2AF1 and SF3B1), chromatin remodeling (ASXL1) and gene transcription (BCOR)." (PMID 38528080, 2024). "Although the growing interest in spliceosome mutation effects, it is not yet clear what the functional role of the mutated SF3B1 protein is in the development of clonal hematopoiesis and risk for hematologic malignancies." (PMID 36230848, 2022). "Along with SF3B1 mutations, recurrent missense mutations in U2 small nuclear RNA auxiliary factor 1 (U2AF1) and serine/arginine-rich splicing factor 2 (SRSF2) were discovered in hematological malignancies, and later reported to be present in some solid tumors." (PMID 31634348, 2019). "Further, our data suggest that mutations of SF3B1 impact immune gene expression independent of cell type, providing new insights into the role of SF3B1K700E in hematologic malignancies." (PMID 41406100, 2025). "Since, in addition to SF3B1, mutations in U2AF1 and SRSF2 have also been observed in hematological malignancies, UM without a SF3B1 mutation—but with the characteristic chromosomal pattern—might harbor mutations in one of these genes." (PMID 31426461, 2019).
blood cancer (8 papers, 2020 to 2025). "Intriguingly, in blood and non-blood cancers with the SF3B1 mutation, immune pathways are among the top downregulated pathways." (PMID 41406100, 2025). "Whether SF3B1 mutations would confer sensitivity to copper ionophores in other hematologic neoplasms and solid tumors is of great interest and requires further evaluation." (PMID 38517966, 2024). "For instance, SF3B1 is highly relevant to blood cancer and can be studied solely as a therapeutic target." (PMID 36792691, 2023). "Previous studies reported that disrupted splicing due to SF3B1 or U2AF1 mutation involves hematopoietic malignancy, HM, and heme biosynthesis in MDS or other blood cancers." (PMID 35085775, 2022). "SF3b1 is a highly conserved HEAT repeat (HR)-containing protein and most of these blood cancer mutations cluster in a hot spot located in HR4-8." (PMID 32320410, 2020). "In addition, the SF3B1 mutations in blood cancers destabilize the SF3B1—SUGP1 interaction in humans, and their equivalent mutations in the yeast SF3B1-homolog Hsh155 lead to altered Hsh155—Prp5 interaction." (PMID 34723968, 2021).
infection (5 papers, 2015 to 2024). The state of being infected such as from the introduction of a foreign agent such as serum, vaccine, antigenic substance or organism. "We found that MDS patients with DM have a higher frequency of TET2 and SF3B1 mutations and an inferior prognosis, which may be caused by the higher incidence of infection." (PMID 38305890, 2024). "We generated cultures containing a tetracycline inducible system expressing hairpins targeting Luciferase or SF3B1 (TR-shSF3B1#3 and an additional hairpin, TR-shSF3B1#5), enabling us to discriminate SF3B1 suppression from infection with shRNA vectors." (PMID 28177281, 2017). "MDS patients with DM have an inferior prognosis which may due to higher infection incidence, with TET2 and SF3B1 mutations being more frequent in those cases." (PMID 38305890, 2024). "Furthermore, two of the proteins, PHF5A and SF3B1, were coimmunoprecipitated with AAV capsids after infection." (PMID 27252527, 2016).
hematologic cancers (4 papers, 2019 to 2022). "Mutations in splicing machinery, such as SF3B1, are connected with splicing pattern changes in hematological cancers." (PMID 36535935, 2022). "The Hsh155/SF3B1 mutations implicated in hematologic cancers, map on the C-terminal part of its HEAT (huntingtin elongation factor 3 protein phosphatase 2A, target of rapamycin 1) -repeat structure." (PMID 31640290, 2019). "Hence, due to the variability of SF3B1 mutations in solid and hematologic cancers, experiments that query the consequence of the SF3B1 R625 mutation in mucosal melanocytes are needed to understand mis-spliced targets and tumorigenic oncogenic mechanisms related to SF3B1 mutations in MM." (PMID 34350118, 2021).
neurodevelopmental disorder (2 papers, 2015 to 2026). A behavioral and cognitive disorder with onset during the developmental period that involves impaired or aberrant development of intellectual, motor, or social functions. "We describe here a cohort of 26 individuals with neurodevelopmental disorders, harbouring SF3B1 constitutional heterozygous variants that appeared mostly de novo." (PMID 41577671, 2026).
kidney disease (1 paper, 2020). "Rather, the top gene from the classic runs is Sf3b1, which is only tangentially associated with kidney disease via copy number variation, through no known mechanism." (PMID 32998684, 2020).
SF3B1 also shares sentences with these, for which no sentence is quoted: mucosal (7 papers); acral melanomas (3); blue nevus (3); myeloma (3); polycythemia vera (3); chronic lymphoid leukemia (2); COVID-19 (2); esophageal cancer (2); genetic diseases (2); head and neck cancer (2); mastocytosis (2); papillary breast cancers (2); renal carcinoma (2); retinitis pigmentosa (2); acute liver failure (1); adenoid cystic carcinoma (1); alcohol dependence (1); amyotrophic lateral sclerosis (1); anal tumors (1); arterial hypertension (1); atypical chronic myeloid leukemia (1); Bardet-Biedl syndrome (1); bladder urothelial carcinomas (1); bone tumors (1); cancer of the eye (1); cardiovascular disease (1); cervical tumor (1); cholangiocarcinoma (1); conjunctival melanomas (1); depression (1).
A further 45 diseases each share a sentence with SF3B1 in 1 paper.